PTPN12 (protein tyrosine phosphatase non-receptor type 12)
Description:
Dephosphorylates a range of proteins, and thereby regulates cellular signaling cascades. Dephosphorylates cellular tyrosine kinases, such as ERBB2 and PTK2B/PYK2, and thereby regulates signaling via ERBB2 and PTK2B/PYK2. Selectively dephosphorylates ERBB2 phosphorylated at 'Tyr-1112', 'Tyr-1196', and/or 'Tyr-1248'.
Synonyms: PTPG1; PTP-PEST
Tractability: Small molecule: a high-quality ligand is known; it belongs to a druggable protein family. Antibody: the Human Protein Atlas places it where antibodies can reach. PROTAC: ubiquitination databases record sites on it; its protein half-life has been measured; a small molecule that binds it is known.
Target class: Tyrosine protein phosphatase; Enzyme; Phosphatase; Protein Phosphatase
Gene: Protein-coding gene on chromosome 7 (77,537,295 to 77,640,072, forward strand). Ensembl gene ENSG00000127947.
Subcellular location: Cytoplasm; Cell junction, focal adhesion; Cell projection, podosome
Subcellular location (Human Protein Atlas): Plasma membrane; Cytosol
Pathways (Reactome):
Signal Transduction: Downregulation of ERBB2 signaling; EGFR downregulation; SHC1 events in ERBB2 signaling; Signaling by PDGF
Disease: Constitutive Signaling by Overexpressed ERBB2
Immune System: Interleukin-37 signaling
Gene Ontology:
Molecular function: phosphoprotein phosphatase activity; protein binding; protein tyrosine phosphatase activity; SH3 domain binding; non-membrane spanning protein tyrosine phosphatase activity
Biological process: cellular response to epidermal growth factor stimulus; peptidyl-tyrosine dephosphorylation; protein dephosphorylation; regulation of epidermal growth factor receptor signaling pathway; negative regulation of ERBB signaling pathway; negative regulation of platelet-derived growth factor receptor-beta signaling pathway; tissue regeneration
Cellular component: cytoplasm; cytosol; nucleoplasm; nucleus; focal adhesion; podosome
Genetic constraint (gnomAD): Loss-of-function variants: 16 observed, 47.38 expected, observed/expected ratio (o/e) 0.34, 90% interval 0.23 to 0.51. The upper end of that interval is the gene's LOEUF score, 0.51, which puts it in group 2 of 6, group 1 being the genes least tolerant of losing a copy. Missense variants: 618 observed, 621.43 expected, observed/expected ratio (o/e) 0.99, 90% interval 0.93 to 1.06. Synonymous variants: 226 observed, 213.69 expected, observed/expected ratio (o/e) 1.06, 90% interval 0.95 to 1.18.
Homologues: Orthologues: chimpanzee PTPN12 (99% identical), macaque PTPN12 (98% identical), pig PTPN12 (92% identical), dog PTPN12 (92% identical), rabbit PTPN12 (88% identical), mouse Ptpn12 (84% identical), rat Ptpn12 (82% identical), tropical clawed frog ptpn12 (58% identical). Paralogues in human: PTPN22 (35% identical), PTPN18 (22% identical), PTPRF (18% identical), PTPRG (18% identical), PTPRS (18% identical), PTPRA (18% identical), PTPRK (18% identical), PTPRD (18% identical), PTPRT (18% identical), PTPRM (17% identical), PTPRZ1 (17% identical), PTPRE (16% identical), and 23 more.
Diseases named in the same sentence as PTPN12 in open-access papers:
PTPN12 is named in the same sentence as 67 diseases in open-access papers, as found by Europe PMC text mining. Sharing a sentence is not in itself a finding about the gene and the disease. The quoted sentences say what the papers report.
breast carcinoma (19 papers, 2012 to 2024). "PTPN12 phosphatase function is compromised in breast cancer by inactivating mutations, deletions, or loss of expression, leading to the overactivation of multiple RTKs, particularly in triple-negative breast cancer (TNBC) subsets." (PMID 38612874, 2024). "PTPN12 is a tumor suppressor, whose frequent loss in aggressive breast cancers activates HER2 and EGFR and accelerates breast carcinogenesis and metastasis." (PMID 38886396, 2024). "In breast cancer, recent findings also indicate that the loss of PTPN12 phosphatase function activates several oncogenic RTKs such as MET, PDGFRb, HER2, and EGFR, positioning PTPN12 as a master regulator of protein tyrosine kinases." (PMID 38612874, 2024). "The downregulation and loss-of-function mutations of PTPN12 were shown in a variety of cancers, including breast cancer." (PMID 38612874, 2024). "In breast cancer, PTPN12 loss resulted in a block in apoptosis and increased migration and invasion." (PMID 29872503, 2018). "Restoring PTPN12 expression in breast cancer cells exhibiting PTPN12 deficiency suppresses proliferation, tumorigenesis, and metastasis." (PMID 29278368, 2017). "PTPN12, one member of the PTP family, has been identified as a potent tumor suppressor in human breast cancer and loss of PTPN12 phosphatase activity leads to aberrant acinar morphogenesis and cellular transformation in mammary epithelial cells." (PMID 24475046, 2014). "Loss of PTPN12 promotes in vivo tumor progression of the implanted breast cancer cells, which express a constitutively active form of ErbB2 (CA-ErbB2), and correlates with the impaired feedback regulation of RTKs, thereby resulting in their aberrant activation." (PMID 33050232, 2020). "Interestingly, in breast cancer cells with loss of PTPN12 expression, restoring PTPN12 expression suppresses proliferation, tumorigenesis and metastasis." (PMID 25868976, 2015). "Reduced PTPN12 expression correlates with improved breast cancer patient outcome on Kaplan–Meier analysis (p = 0.00651), supporting a tumor suppressor role for PTPN12 in human breast cancer." (PMID 38886396, 2024). "Furthermore, considering the contrasting roles of PTPN12 and YAP/TAZ in breast cancer, it would be intriguing to investigate whether there is a reverse correlation between the levels of PTPN12 and YAP/TAZ, as well as if this correlation is linked to poor survival outcomes in breast cancer patients." (PMID 38612874, 2024). "PTPN12, also called PTP-PEST, is a cytosolic phosphatase that has a tumour-suppressor function in breast cancer and renal cell carcinoma." (PMID 38334623, 2024). "Due to its pivotal role in breast cancer and its function as a master regulator of RTKs, we investigated how PTPN12 influences tumorigenesis via the Hippo pathway." (PMID 38612874, 2024). "As for the breast cancer lines, cJun and p27 were recruited to the +2 kb PTPN12 site in a p27-dependent manner, with higher enrichment in UMUC3 overexpressing p27CK-DD than in vector control and loss of cJun binding upon p27 knockdown UMUC3-LuL2." (PMID 38886396, 2024). "It presents compelling evidence that PTPN12 modulates cell proliferation by affecting the Hippo effector proteins YAP and TAZ, suggesting a potential strategy for treating breast cancer patients with compromised PTPN12." (PMID 38612874, 2024). "For instance, in breast cancer, PTPN12 inhibits the malignant transformation of human mammary normal epithelial by down-regulation of growth factor receptor signaling pathway." (PMID 37333450, 2023). "For instance, PTPN12 can effectively inhibit the tumorigenicity and metastasis of breast cancer cells." (PMID 35290144, 2022). "For instance, PTPN1 in hepatocellular carcinoma, PTPN11 in colon cancer and PTPN12 in breast cancer can be both tumor promoters and tumor suppressors based on different molecular pathways." (PMID 35957898, 2022).
breast carcinoma (continued). "Recently, it was uncovered that PTPN12 is a tumor suppressor in human breast cancer and lung cancer, seemingly as a result of its capacity to control receptor PTK signaling." (PMID 25663493, 2015). "In recent years, decreased expression of PTPN12 has been shown to be correlated with the development and progression of different human cancers, including breast cancer, hepatocellular carcinoma, and esophageal squamous cell carcinoma." (PMID 25663493, 2015). "Recently, there is an increasing body of evidence that decreased expression of PTPN12 occurs in various human malignancies, including breast cancer, colon cancer, ovarian cancer and esophageal squamous cell carcinoma." (PMID 24475046, 2014). "With regard to the prognostic impact of PTPN12 on other human cancers, similar findings have been reported in breast cancer and esophageal cancer." (PMID 24475046, 2014). "In recent years, decreased expression of PTPN12 has been found in several human cancers and correlated with the aggressiveness and/or poor prognosis of breast cancer and esophageal cancer." (PMID 24475046, 2014). "It has reported that PTPL1/PTPN13 regulated breast cancer cell aggressiveness through a direct inactivation of Src kinase and PTPN12 inhibits breast cancer metastasis through multiple targets including EGFR1, Her2 and Src kinase." (PMID 22394684, 2012). "In addition, several studies have shown that PTPN12 is linked to a favorable prognosis in TNBC patients by suppressing multiple oncogenic tyrosine kinases, including HER2 and EGFR, thereby dampening breast cancer cell survival, migration and EMT." (PMID 35957898, 2022). "Although a mechanism to explain these findings has not been identified, it is evident that PTPN12 may serve as a useful biomarker as an oncogene in prostate cancer, which contradicts the way PTPN12 functions in breast cancer." (PMID 34884670, 2021). "PTPN12-null breast cancer cells were also found to have enhanced metastatic potential." (PMID 29872503, 2018). "Of a total number of four candidates, we selected PTPN12 for a further experiment and validation because it has previously been shown to play an important role in breast cancer initiation and progression, which is similar to the role of the Hippo pathway in breast cancer." (PMID 38612874, 2024). "Recently, another pathway has been described in a breast cancer model, where CD99-derived agonist ligands inhibit fibronectin-mediated β1 integrin activation, through the SHP2/ERK/PTPN12/FAK1 signaling pathway." (PMID 30845661, 2019). "Recently, PTPN12 was found to interact with and dephosphorylate the RTKs EGFR and ErbB-2, thereby acting as a tumor suppressor in breast cancer by suppressing MAPK signaling." (PMID 23785422, 2013). "PTPN12 repression facilitates STAT3 activation by Pyk2 and ES-TF expression, and the observed p27-driven increases in mammospheres and in tumor formation by breast cancer initiating cells in vivo." (PMID 38886396, 2024). "Approximately 23% of breast cancer patients exhibit low or no expression of PTPN12, particularly in triple-negative breast cancer patients, which predicts a poor prognosis." (PMID 37333450, 2023). "Abnormal activation of PTKs and absence of PTPN12 have been observed in breast cancer, lung cancer, and brain malignancies." (PMID 37333450, 2023). "Taken together, these results indicate that CD99-derived agonist ligand inhibits epidermal growth factor (EGF)-induced EGFR dimerization through impairment of cytoskeletal reorganization by PTPN12-dependent c-Src/FAK inactivation, thereby suppressing breast cancer growth." (PMID 33050232, 2020). "Subsequent experiments validated PTPN12, a master regulator of oncogenic receptor tyrosine kinases (RTKs), as a previously unrecognized negative regulator of the Hippo pathway effectors, oncogenic YAP/TAZ, influencing breast cancer cell proliferation and migration." (PMID 38612874, 2024).
breast carcinoma (continued). "Another PTP, known as protein tyrosine phosphatase non-receptor type 12 (PTPN12), is a tyrosine-specific, non-receptor type PTP that exhibits tumor suppressor activity in breast cancer by inhibiting certain RTKs including HER2 and EGFR." (PMID 34884670, 2021). "CD99CRIII3 dose-dependently suppressed the growth of MDA-MB-231 human breast cancer cells implanted in nude mice, while it failed to suppress the growth of shPTPN12-MDA-MB-231 cells implanted in nude mice, suggesting that PTPN12 serves as a key executor of the CD99 signaling pathway." (PMID 33050232, 2020).
hepatocellular carcinoma (9 papers, 2014 to 2022). A malignant tumor that arises from hepatocytes. "PTPN12 suppresses progression of multiple cancers and is negatively controlled by miR-106a-5p in hepatocellular carcinoma, miR-503 in retinoblastoma, miR-194 in ovarian cancer, and miR-200b in colon cancer." (PMID 35957898, 2022). "In hepatocellular carcinoma cells, PTPN12 regulates epithelial–mesenchymal transition which contributes to chemoresistance and metastasis." (PMID 32536826, 2020). "Correlation of PTPN12 expression with patients' clinicopathological features in primary hepatocellular carcinomas." (PMID 24475046, 2014). "Univariate analysis of PTPN12 expression and clinicopathologic variables in 248 patients with primary hepatocellular carcinoma (Cox proportional-hazards regression)." (PMID 24475046, 2014). "PTPN12 plays a critical role in tumor deterioration of TNBC, and PTPN12 is an independent prognostic factor for hepatocellular carcinoma (HCC)." (PMID 35154122, 2022).
triple-negative breast carcinoma (8 papers, 2015 to 2024). An invasive breast carcinoma which is negative for expression of estrogen receptor (ER), progesterone receptor (PR), and human epidermal growth factor receptor 2 (HER2). "With respect to inactivation of PTP by hyper-oxidation in ROS-mediated carcinogenesis, PTPN12 has been suggested as a tumor suppressor in triple-negative breast cancer." (PMID 30126387, 2018). "PTPN12 exhibited relatively low expression levels in triple-negative breast cancer (TNBC) cells." (PMID 33050232, 2020). "PTPN12 is a tumor suppressor that inhibits multiple receptor tyrosine kinases, including epithelial growth factor receptor (EGFR) and HER2 in triple-negative breast cancer." (PMID 35136055, 2022). "Protein tyrosine phosphatase non-receptor type 12 (PTPN12) are signaling molecules that regulate a variety of cellular processes and has been found to be epigenetically regulated in triple-negative breast cancer." (PMID 32711505, 2020). "Previous findings suggested that PTPN12 suppresses the growth and metastasis of human Triple negative breast cancer (TNBC) cells and that such function is lost by nonsynonymous mutations." (PMID 29278368, 2017).
colon carcinoma (6 papers, 2014 to 2022). "For example, AD, PD, and MND were all associated with SNPs in LAMA2, PTPN12, and SPATA7, which are implicated in muscular dystrophy, colon cancer, and retinitis pigmentosa, respectively." (PMID 35711735, 2022). "Recent studies showed that PTPN12 inhibits growth, proliferation, tumorigenicity, and metastatic potential in triple-negative breast cancer and colon cancer, and also found to be a prognostic biomarker for esophageal squamous cell carcinoma." (PMID 25663493, 2015). "Recently, it has been suggested that PTPN12 functions as a suppressor of epithelial cell motility by controlling Rho GTPase activity and the assembly of adherent junctions in colon cancer cells." (PMID 24475046, 2014). "Similarly, decreased expression of PTPN12 in colon cancer cell lines resulted in increased cellular migration." (PMID 29872503, 2018). "Silencing of PTPN12 has been shown to enhance migration in ovarian cancer and colon cancer cells." (PMID 25663493, 2015).
lung carcinoma (6 papers, 2015 to 2022). "The variant miR-124-3 is unable to suppress PTPN12 tumor suppressor and may alternatively behave as a tumor suppressor instead of an oncogene in breast or lung cancer." (PMID 34925466, 2021). "As PTPN12 reduces mammary cell proliferation and transformation, the targeting of PTPN12 by miR-124 suppresses its tumor suppressor behavior which promotes the oncogenic shift in breast and lung cancer." (PMID 34925466, 2021). "Moreover, intravenous administration of sEVs derived from lung cancer cells increased the expression level of PTPN12 and promoted tumor growth and angiogenesis in an animal model." (PMID 35136055, 2022). "sEVs promoted tumor growth and angiogenesis by downregulating PTPN12 expression; however, the miR-494-3p inhibitor significantly suppressed these effects in vivo, confirming that miR-494-3p acts as a major onco-miRNA loaded into lung cancer cell-derived sEVs." (PMID 35136055, 2022).
esophageal cancer (5 papers, 2014 to 2022). A primary or metastatic malignant neoplasm involving the esophagus. "For esophageal carcinoma (ESCA), PTPN1 and PTPN12 levels were correlated with incidence; PTPN20 was associated with poor prognosis." (PMID 32536826, 2020). "Our previous investigation recently demonstrated significantly longer survival durations in esophageal cancer patients with high PTPN12 expression than those with low PTPN12 expression." (PMID 25868976, 2015). "Interestingly, PTPN1 expression is implicated in the incidence of esophageal cancer, while PTPN6 is down-regulated in esophageal cancer and PTPN12 is a favorable prognostic biomarker for patients with esophageal squamous cell carcinoma." (PMID 35957898, 2022). "Additionally, western blotting result indicated that the expression of PTPN12 protein was lower in esophageal cancer tissues than that in adjacent esophageal tissues." (PMID 24475046, 2014). "However, former research indicated that PTPN12 may serve as a potential prognostic indicator for esophagus cancer patients." (PMID 32536826, 2020). "CCLE analyses showed that in esophagus cancer cell lines, PTPN1, PTPN4 and PTPN12 were highly expressed; in gastric cancer cell lines, PTPN2 and PTPN12 were highly expressed; in colorectal cancer cell lines, PTPN12 was highly expressed while PTPN22 was downregulated." (PMID 32536826, 2020).
glioblastoma (5 papers, 2011 to 2021). The most malignant astrocytic tumor (WHO grade IV). "The PXN and PTPN12 mRNA expression increased in glioblastomas compared to normal brain, and in the case of PTPN12, the expression was higher in glioblastomas compared to astrocytomas grades II and III." (PMID 33841333, 2021). "Consistent with this proposed function, PTPN12 mRNA levels are down-regulated in invasive intratumoral regions of glioblastoma." (PMID 33710332, 2021). "miR-124 controls self-renewal and tumorigenic competence of human glioblastoma cells by targeting PTPN12 phosphatases." (PMID 26041995, 2015). "A number of these variants involve the protein phosphatase PTPN12 suggesting that deregulation of PTPN12, via a variety of rearrangements, is common in glioblastoma." (PMID 21510904, 2011). "A number of the somatic CNV predictions in GBM involve the protein phosphatase PTPN12, suggesting that deregulation of PTPN12 via a variety of rearrangements is common in glioblastoma." (PMID 21510904, 2011). "In line with its function at focal adhesions, PTPN12 suppresses glioblastoma invasion." (PMID 33710332, 2021). "Bioinformatic analysis revealed that PXN and PTPN12 mRNA expression was higher in astrocytomas (Grades II, III, and IV) compared to normal brain and showed the highest expression in the mesenchymal subtype (the most aggressive glioblastoma subtype, associated with bad prognostic)." (PMID 33841333, 2021). "PXN and PTPN12 expression data from 196 grade II, 223 grade III, and 139 grade IV (glioblastoma) astrocytomas were obtained from TCGA and compared to 249 healthy human brain cortex samples from the GTEx database." (PMID 33841333, 2021). "The analysis of expression among the four subtypes of glioblastomas showed that PXN and PTPN12 have the highest levels of expression in the mesenchymal subtype (the most aggressive glioblastoma subtype)." (PMID 33841333, 2021). "SCP1 down-regulation induces neurogenensis, and miR-124 contributes to this process in part by targeting it.miR-124 controls self-renewal and tumorigenic competence of human glioblastoma cells by targeting SCP1 and PTPN12 phosphatases." (PMID 26041995, 2015). "It was reported that miR-124 controls self-renewal and tumorigenic competence of human glioblastoma cells by targeting SCP1 and PTPN12 phosphatases." (PMID 26041995, 2015).